INS (insulin)
Diseases named in the same sentence as INS in open-access papers (continued):
Sharing a sentence is not in itself a finding about the gene and the disease.
Insulin resistance (continued). "Because of the central role of the liver in the whole-body energy homeostasis, liver insulin sensitivity and its potential relationship with mitochondrial oxidative phosphorylation appear to be crucial in the development of insulin resistance." (PMID 22457831, 2012). "For to determine the effect of Diamel on the insulin resistance, insulin sensitivity, and sexual hormones results in women with polycystic ovary syndrome (PCOS)." (PMID 22778733, 2012). "Several studies have demonstrated that the hypersecretion of insulin is a primary defect of type 2 diabetes and that insulin resistance develops secondarily to chronic hyperinsulinaemia." (PMID 22470480, 2012). "Hepatic insulin resistance is considered the major determinant of fasting hyperglycemia and the current data suggest enhanced hepatic insulin sensitivity in our growth restricted females." (PMID 23028837, 2012). "Obesity, in particular abdominal obesity, was pointed out as a primary contributor to acquired insulin resistance, as increasing adiposity is correlated with impaired insulin action, and participated to an increased occurrence of type 2 diabetes." (PMID 22457831, 2012). "Insulin resistance is a metabolic condition involving reduced sensitivity of insulin-sensitive tissues to insulin-induced glucose disposal, including adipose tissue, skeletal muscle, and liver." (PMID 26486919, 2012). "In T2DM, beta-cells become unable to adequately increase insulin release to compensate insulin resistance and consequently leading to a situation of hyperglycemia." (PMID 23162532, 2012). "Insulin resistance is the reduced response of a target tissue (including skeletal muscle, adipose tissue, etc.)to insulin as compared to a healthy control." (PMID 22474580, 2012). "This is followed by progressively increasing insulin resistance in the second and third trimesters with a borderline increase of insulin production or hyperinsulinemia." (PMID 22518122, 2012). "The euglycemic-hyperinsulinemic clamp was used to determine insulin sensitivity in the diet models, as in previous studies we have shown that high fat diet fed mice have insulin resistance as determined by this technique." (PMID 23201760, 2012). "Treatment with telmisartan significantly improved the hyper-insulin response to glucose loading in patients with hypertension and obesity showing insulin resistance." (PMID 22594344, 2012). "In genome-wide scans to date, the majority of the genetic variants for type 2 diabetes identified in European-derived populations appeared to be related to impaired insulin secretion, while only IRS1 has been unequivocally associated with insulin resistance." (PMID 22438884, 2012). "Beta-cell failure (insufficient insulin secretion) and insulin resistance (impaired action of insulin to stimulate glucose uptake) precede the development of type 2 diabetes." (PMID 22988521, 2012). "Insulin resistance is common in individuals with obesity or type 2 diabetes (T2D), in which circulating insulin levels are frequently increased." (PMID 22701472, 2012). "Increase in sugar or refined carbohydrate consumption results in an increase of insulin and insulin resistance that can lead to the accumulation of fat in the liver." (PMID 22969728, 2012). "Insulin resistance is a pathological condition in which insulin action is impaired in peripheral target tissues including skeletal muscle, liver, and adipose tissue." (PMID 22701472, 2012). "Studies showing that liver fat content affects insulin sensitivity in humans more strongly than visceral fat support a direct and important role of fatty liver in the pathogenesis of insulin resistance." (PMID 22194737, 2012). "This insulin-resistance state was improved by PLC treatment since the animals receiving this carnitine derivate significantly reduced plasmatic insulin and HOMAIR (P<0.001 vs vehicle-HF) and fasting glucose was not significantly different to vehicle-ST." (PMID 22457831, 2012).
Insulin resistance (continued). "This antagonist was also able to increase whole body insulin sensitivity and reverse plasma fatty acids composition changes in a rat model of insulin resistance." (PMID 23024762, 2012). "Insulin resistance produces a sustained increase in demand for insulin, and, over time, the β cells are unable to sustain the augmented levels of insulin biosynthesis and secretion." (PMID 22518128, 2012). "PR administration ameliorated fasting plasma levels of glucose, insulin, and homeostasis model assessment of insulin resistance (HOMA-IR)." (PMID 22829857, 2012). "Here, we summarize the diverse roles of PTMs in insulin-sensitive tissues and their involvement in the pathogenesis of insulin resistance." (PMID 22110478, 2012). "Nevertheless, our early observations corroborate data from older animals demonstrating both insulin resistance in prenatally dexamethasone exposed rats and improved insulin sensitivity at adulthood in perinatally malnourished animals devoid of catch-up growth." (PMID 23166830, 2012). "Although leptin initially increases insulin sensitivity, long-term exposure to high leptin levels has been reported to result in insulin resistance." (PMID 23056516, 2012). "Muscle SOCS3 is therefore positioned to play an important role in the pathogenesis of obesity-induced insulin resistance and type 2 diabetes by antagonizing both leptin and insulin signaling in skeletal muscle." (PMID 23115649, 2012). "In the present study, insulin resistance seemed to be higher during SG than LG, as shown by a higher insulin/glucose ratio, which approached the threshold of a hyperinsulinemic response (18 pmol/mmol)." (PMID 23031354, 2012). "Genotyping of T−786→C eNOS gene promoter, fasting glucose, insulin, and insulin resistance (defined as HOMA-IR index > 2.5) were determined in all patients." (PMID 23031426, 2012). "Increased insulin resistance post supplementation was observed in a cohort of middle-aged adults, and increased insulin sensitivity in first time GDM patients." (PMID 22809461, 2012). "T2DM is characterized by a combination of insulin resistance and a compensatory response to inadequate insulin secretion, which leads to the characteristic hyperglycemia." (PMID 22309804, 2012). "In old case reports, infusing chromium to critically ill patients with severe insulin resistance has improved their insulin requirements significantly." (PMID 23882364, 2012). "Anti-TNF therapy improved insulin sensitivity and reversed defects in the insulin signaling cascade in RA patients with active disease and high insulin resistance." (PMID 22691241, 2012). "They improve insulin sensitivity by up-regulating adipogenesis, decreasing free fatty acid levels, and reversing insulin resistance." (PMID 23150952, 2012). "Exercise can increase skeletal muscle sensitivity to insulin, improve insulin resistance and regulate glucose homeostasis in rat models of type 2 diabetes." (PMID 23272147, 2012). "SOCS3 is increased in inflammation and is thought to contribute to the pathogenesis of insulin resistance by inhibiting insulin signaling." (PMID 22761701, 2012). "Insulin levels increase to compensate for progressing insulin resistance leading to decreased glucose uptake and glucose utilization." (PMID 22978376, 2012). "TZDs increase insulin action in diverse animal models of insulin resistance and also in patients with T2D." (PMID 22745632, 2012). "Collectively, these transcriptional alterations can impair insulin signaling pathways leading to insulin resistance and the development of type 2 diabetes." (PMID 22203837, 2012). "Concentration of 25(OH) D, calcium, phosphorous, parathyroid hormone (PTH), fasting blood glucose, HbA1c, serum insulin, homeostasis model assessment of insulin resistance (HOMA-IR) was determined in the fasting samples." (PMID 23497722, 2012).
Insulin resistance (continued). "In a mouse model of diet-induced obesity and insulin resistance, chronic sildenafil treatment was able to improve insulin action and decrease body mass." (PMID 23028874, 2012). "Among adolescents, Goodman and colleagues showed education related differences in insulin, glucose, insulin resistance (HOMA-IR), and also in HDL and LDL." (PMID 22852830, 2012). "In contrast, in case of insulin resistance and an unphysiological release of insulin and proinsulin from the beta cells, the signal shifts from the vasoprotective PI-3 K pathway to the mitogen activated proteinkinase (MAPK) pathway." (PMID 22577369, 2012). "Anti-TNF-α treatment apparently ablates insulin resistance via restoration of normal tyrosyl phosphorylation dependent insulin signaling." (PMID 22606220, 2012). "Hyperglycemia-induced oxidative stress results in reducing glucose uptake from blood by muscle cells and develops into insulin resistance by decreasing insulin secretion from pancreatic β-cells." (PMID 22520940, 2012). "JNK and IKK are the key stress-activated kinases to disrupt insulin signal transduction by serine-phosphorylating IRS1/2 leading to insulin resistance in HFat-fed mice." (PMID 22355328, 2012). "Biologically, obesity is associated with high levels of circulating insulin, decreased insulin sensitivity, and insulin resistance." (PMID 23050155, 2012). "Nevertheless, the admittedly weak association of the rs225338 A allele with worse insulin resistance we report in our study may reinforce the rationale to investigate more thoroughly the relationship of this gene, or of a closely related region, with the mechanisms modulating insulin sensitivity." (PMID 22427875, 2012). "Insulin resistance seems to be associated with a predominantly Th1 cytokine pattern: TNF-α (and to a lesser extent IL-1 and IL-6), produced by visceral fat among others, inhibits insulin signaling pathways, leading to insulin resistance." (PMID 23204981, 2012). "Peripheral insulin resistance emanates from interplay between three major organs, viz., liver, adipose tissue and skeletal muscles, with altered insulin signaling that stems from altered insulin receptors and post-receptor defects at the molecular level." (PMID 22649556, 2012). "The 90% pancreatectomized model is more similar to the etiology of the Asian form of type 2 diabetes with the surgery resulting in impaired insulin secretion, but with diet-induced insulin resistance developing simultaneously or shortly thereafter." (PMID 22550941, 2012). "In summary, we demonstrate that muscle-specific over-expression of SOCS3 impairs muscle insulin signaling and promotes systemic insulin resistance." (PMID 23115649, 2012). "In normal individuals, insulin resistance is compensated by an up-regulation of insulin secretion to maintain normal glucose tolerance." (PMID 23015803, 2012). "In this study we explored the molecular basis of insulin resistance beyond the known role of insulin signaling genes, and, implicitly screened for novel candidate T2D genes." (PMID 23236286, 2012). "A 30-min IPGTT at week 11 similarly showed reduced glucose tolerance in HC mice as evidenced by raised plasma insulin and glucose at baseline and at 20 and 30 min postinjection, suggesting the presence of insulin resistance." (PMID 21543215, 2012). "Estrogen is reported to improve glucose homeostasis by potentiating glucose-stimulated insulin secretion and attenuates insulin resistance." (PMID 23270397, 2012). "A reduction in circulating insulin levels has been observed after RYGB surgery with improved insulin sensitivity as measured by homeostasis model assessment of insulin resistance (HOMA-IR)." (PMID 22619730, 2012). "In epidemiological studies in humans, BPA levels were found to be associated with abnormal liver function enzymes, higher levels of fasting glucose, insulin, and HOMA-IR insulin resistance, all are factors known to be associated with hypertension development." (PMID 22363351, 2012).
Insulin resistance (continued). "Even though the association between the severity of insulin resistance and HCV viral load or genotype is controversial, viral eradication by antiviral therapy actually improves insulin sensitivity." (PMID 22701799, 2012). "Before type 2 diabetes is diagnosed, insulin resistance can be present for years, thereby increasing insulin and glucose concentrations." (PMID 23300589, 2012). "Accordingly, the deterioration of this insulin-induced NO release is frequently found in the insulin resistance state and of particular interest is the increase of muscle NO availability reported in this study with PLC treatment." (PMID 22457831, 2012). "When PPARγ expression in macrophages was ablated in mice, this resulted in systemic insulin resistance with attenuated insulin sensitizing effects of TZDs." (PMID 22529965, 2012). "Defective insulin mediated fatty acid suppression also is suggested to induce insulin resistance in type 1 diabetes individuals." (PMID 23185996, 2012). "Nutrient overload, in particular increased fat and elevated circulating amino acids, have been shown to cause β-cell compensation and increased activation of mTOR which can lead to insulin resistance in peripheral insulin-responsive tissues." (PMID 22974011, 2012). "Although there are many aspects that are still needed to be identified between the link of lipotoxicity and insulin resistance, it is well known that an increase in intracellular lipid levels leads to a decrease in insulin action." (PMID 22574901, 2012). "Some studies have assessed the effects ofhyperinsulinemia and insulin resistance in relationship with insulin sensitizing agentssuch as Metformin (Met)." (PMID 25505509, 2012). "Apelin is increased in relation to the worsening of insulin-resistance/insulin-secretion, as in the diabetic status, and this increase has been suggested as a possible compensatory mechanism." (PMID 23227256, 2012). "Insulin resistance is defined clinically as the inability of a known quantity of exogenous or endogenous insulin to increase glucose uptake and utilization in an individual as much as it does in a normal population." (PMID 22792101, 2012). "Palmitate has been reported to induce insulin resistance by increasing PTP1B expression in the insulin target tissues." (PMID 22728372, 2012). "In response to the systemic insulin resistance, pancreatic β-cells increase insulin hypersecretion accelerating liver fat accumulation and leading to NAFLD." (PMID 23112961, 2012). "Hepatic insulin resistance stimulates lipolysis, and lipolysis leads to increased generation of toxic lipids e.g. ceramides, which further impair insulin signaling, mitochondrial function, and cell viability." (PMID 22329651, 2012). "In contrast, while targeted deletion of SOCS3 in liver-enhanced liver insulin sensitivity on chow diet, it accelerated the onset of high-fat diet- or age-induced insulin resistance with an increased inflammation in liver." (PMID 23316186, 2012). "Increased PKC would affect insulin signaling leading to insulin resistance, hyperinsulinemia, and hyperglycemia." (PMID 21869929, 2012). "In the Gypsy group, the values of triglycerides, atherogenic index, insulin, insulin resistance were significantly increased and the level of HDL-cholesterol was significantly decreased." (PMID 23390466, 2012). "Since, HOMA-IR incorporates both glucose and insulin concentrations and represents insulin resistance, which can promote atherosclerosis trough several mechanisms, it might be more strongly associated with cardiovascular disease than individual glucose or insulin concentrations." (PMID 23300589, 2012). "Decreased adiponectin and IGFBP-1 levels and increased triglyceride levels are considered to reflect impaired insulin sensitivity and predict insulin resistance." (PMID 23186039, 2012). "The pro-insulin level is used as a marker of insulin resistance and is often used in a pro-insulin/insulin ratio as an indicator of β-cell dysfunction." (PMID 23110768, 2012).
Insulin resistance (continued). "This was associated with other features of the metabolic syndrome: fasting hyperglycemia, a markedly abnormal glucose tolerance test, fasting hyperinsulinemia, impaired response to insulin (insulin resistance) and arterial hypertension." (PMID 22509248, 2012). "While cis-9, trans-11 CLA improves insulin sensitivity, trans-10, cis-12 CLA causes insulin resistance." (PMID 21869929, 2012). "The causative role of elevated iron store levels in the onset of insulin resistance is well established by prospective data as well as evidence that blood donations improve insulin sensitivity by decreasing iron stores." (PMID 22848554, 2012). "Conversely, liver fat content correlates with hepatic insulin resistance, and decreasing the hepatic lipid concentration can improve insulin sensitivity." (PMID 22272317, 2012). "Their insulin resistance was possibly less pronounced, as supported by lower insulin concentrations, lower insulin/glucose ratios, and higher glucose clearance rates (n = 8, 5.0 ± 1.4 mL/kg per minute; unpublished data)." (PMID 23031354, 2012). "Adipose cell size also correlated with other known metabolic consequences of insulin resistance including circulating insulin levels and total triglyceride levels." (PMID 22992414, 2012). "Clearly defining the role of cytokines in reduced insulin sensitivity of horses will be a very important step in determining how obesity and insulin resistance are related." (PMID 26486919, 2012). "In conclusion the food supplement Diamel reduces insulin resistance and improves insulin sensitivity in a small sample of women with PCOS and shows promise to be a nonmedical alternative if our findings are confirmed in larger randomized control trials." (PMID 22778733, 2012). "Recently, it was demonstrated that SP-D expression is significantly increased in pancreatic β-cells under conditions of pregnancy-induced insulin resistance and in newly formed β-cells making the molecule a specific marker for new insulin producing cells." (PMID 22509382, 2012). "Insulin resistance develops when the concentration of insulin in blood is insufficient to efficiently regulate glucose uptake." (PMID 22451839, 2012). "Adiponectin has also been studied in animal experiments in which it was demonstrated that it can reduce insulin resistance and enhance the action of insulin in liver, resulting in lowering of glucose blood levels." (PMID 22550485, 2012). "We also discuss the clinical significance of insulin sensitizers used to improve insulin resistance and lipid modulators used to manage lipid metabolism as potential treatment options for chronic hepatitis C." (PMID 22701799, 2012). "Plasma levels of the anti-inflammatory cytokine IL-10 have been found to positively correlate with insulin sensitivity and IL-10 treatment protects against diet-induced insulin resistance." (PMID 22470484, 2012). "In conclusion, we have shown that the absence of maternal melatonin during pregnancy and lactation programs the offspring to glucose intolerance mainly due to hepatic insulin resistance and decreased insulin secretion." (PMID 22719949, 2012). "Berbeine has been shown to reduce the weight, enhance the insulin sensitivity, decrease the insulin resistance and decrease the blood glucose in genetic models of type 2 diabetes." (PMID 24250489, 2012). "Protein tyrosine phosphatase-1B, a phosphatase physiologically involved in terminating the insulin signaling cascade, is overexpressed in obesity and insulin resistance." (PMID 21543215, 2012). "Once rats fed a high dose of fructose are considered a nutritional model for insulin resistance, the present study investigated the effects of a high-salt diet in fructose-fed insulin-resistant rats on PON1 and its influence in serum and oxidative parameters." (PMID 22738670, 2012). "T2D occurs in patients who fail to compensate for insulin resistance by increasing insulin secretion." (PMID 21915177, 2012).